PLEKHM3 (pleckstrin homology domain containing M3)
Description:
Involved in skeletal muscle differentiation. May act as a scaffold protein for AKT1 during muscle differentiation.
Synonyms: DAPR; PLEKHM1L
Tractability: Antibody: UniProt places it where antibodies can reach, with medium confidence; its Gene Ontology location is reachable by antibodies, with medium confidence. PROTAC: ubiquitination databases record sites on it.
Gene: Protein-coding gene on chromosome 2 (207,821,288 to 208,025,846, reverse strand). Ensembl gene ENSG00000178385.
Subcellular location: Cytoplasm; Golgi apparatus; Cell membrane
Subcellular location (Human Protein Atlas): Cytosol; Vesicles
Gene Ontology:
Biological process: myoblast differentiation
Cellular component: cytoplasm; Golgi apparatus; plasma membrane
Genetic constraint (gnomAD): Loss-of-function variants: 43 observed, 83.86 expected, observed/expected ratio (o/e) 0.51, 90% interval 0.4 to 0.66. The upper end of that interval is the gene's LOEUF score, 0.66, which puts it in group 2 of 6, group 1 being the genes least tolerant of losing a copy. Missense variants: 788 observed, 972.78 expected, observed/expected ratio (o/e) 0.81, 90% interval 0.76 to 0.86. Synonymous variants: 351 observed, 378.28 expected, observed/expected ratio (o/e) 0.93, 90% interval 0.85 to 1.01.
Homologues: Orthologues: chimpanzee PLEKHM3 (99% identical), macaque PLEKHM3 (99% identical), rat Plekhm3 (92% identical), mouse Plekhm3 (92% identical), pig PLEKHM3 (92% identical), dog PLEKHM3 (91% identical), guinea pig PLEKHM3 (91% identical), rabbit PLEKHM3 (86% identical), tropical clawed frog plekhm3 (61% identical), zebrafish plekhm3 (47% identical), Caenorhabditis elegans cup-14 (22% identical), Drosophila melanogaster Plekhm1 (20% identical). Paralogues in human: PLEKHM1 (26% identical), RUBCN (16% identical), RUBCNL (15% identical), DEF8 (14% identical).
Diseases named in the same sentence as PLEKHM3 in open-access papers:
PLEKHM3 is named in the same sentence as 13 diseases in open-access papers, as found by Europe PMC text mining. Sharing a sentence is not in itself a finding about the gene and the disease. The quoted sentences say what the papers report.
ovarian carcinoma (5 papers, 2019 to 2025). A malignant neoplasm originating from the surface ovarian epithelium. "Here, we found that curcumin inhibited ovarian cancer cell proliferation and promoted apoptosis, and first confirmed it was associated with the regulatory network of circ-PLEKHM3/miR-320a/SMG1." (PMID 34784955, 2021). "Another study reported that curcumin inhibited cell proliferation and increased apoptosis in ovarian cancer by regulating the circ-PLEKHM3/miR-320a/SMG1 axis." (PMID 41010991, 2025). "Conversely, circ-PLEKHM3 has been identified as an inhibitor of ovarian cancer progression by competitively sponging endogenous miR-320a." (PMID 39030638, 2024). "From a translational perspective, experiments have shown that curcumin (turmeric’s active component) can restrain proliferation and facilitate apoptosis in ovarian cancer by regulating the circ-PLEKHM3/miR-320a/SMG21 axis." (PMID 35877430, 2022). "In ovarian cancer, PLEKHM3 is similarly downregulated, where it forms circular RNAs (circ-PLEKHM3) that regulate gene expression (similar to microRNAs) and act as a tumor suppressor." (PMID 35877430, 2022). "A previous report displayed the circ-PLEKHM3 acted as miR-9 sponge to regulate ovarian cancer progression." (PMID 34784955, 2021). "Curcumin restrained proliferation and facilitated apoptosis in ovarian cancer by regulating the circ-PLEKHM3/miR-320a/SMG1 axis." (PMID 34784955, 2021). "In the past research, circ-PLEKHM3 was confirmed to be lowly expressed in ovarian cancer and have inhibitory effects on cell growth and metastasis." (PMID 34784955, 2021). "The regulatory network was complex, and we wanted to explore an additional network mediated via circ-PLEKHM3 in ovarian cancer." (PMID 34784955, 2021). "Here, miR-320a mimic reversed the regulation of circ-PLEKHM3 on curcumin-mediated ovarian cancer cell proliferation and apoptosis, further confirming that circ-PLEKHM3 sponged miR-320a to participate in ovarian cancer progression." (PMID 34784955, 2021). "MiR-320a was found to be evidently upregulated in ovarian cancer tissues and cells, and its expression level in ovarian cancer tissues was negatively correlated with circ-PLEKHM3 expression." (PMID 34784955, 2021). "Circ-PLEKHM3 overexpression exacerbated the effect of curcumin on ovarian cancer cell proliferation and apoptosis, as well as anti-tumor effect." (PMID 34784955, 2021). "In this study, we compared the expression profiles of circRNAs in ovarian cancer and normal ovarian tissues, and found that a circular RNA derived from PLEKHM3 termed circPLEKHM3 is significantly down-regulated in ovarian cancer." (PMID 31623606, 2019). "Circ-PLEKHM3 was downregulated in ovarian cancer, and its expression could be promoted by curcumin treatment." (PMID 34784955, 2021). "Function analysis showed that circ-PLEKHM3 overexpression could aggravate curcumin function by suppressing cell proliferation, triggering apoptosis and reducing tumorigenesis in ovarian cancer." (PMID 34784955, 2021). "To explore whether SMG1 could be regulated via circ-PLEKHM3/miR-320a axis in ovarian cancer cells, we measured SMG1 expression in SKOV3 and A2780 cells co-transfected with oe-circ-PLEKHM3 and miR-320a mimic." (PMID 34784955, 2021). "Here, we found that circ-PLEKHM3 was downregulated in ovarian cancer, and its expression could be promoted by curcumin." (PMID 34784955, 2021). "In conclusion, curcumin could suppress proliferation and promote apoptosis in ovarian cancer, possibly via regulating circ-PLEKHM3/miR-320a/SMG1 axis." (PMID 34784955, 2021). "Therefore, circ-PLEKHM3 might be a key target for the regulation of ovarian cancer progression." (PMID 34784955, 2021). "Low level of circ-PLEKHM3 was measured in ovarian cancer samples in comparison to normal tissues." (PMID 34784955, 2021). "However, it is not clear whether curcumin mediates ovarian cancer progression by regulating the circ-PLEKHM3/miR-320a/SMG1 axis." (PMID 34784955, 2021).
chordoma (1 paper, 2024). Chordomas are rare malignant tumors arising from embryonic remnants of the notochord in axial skeleton. "The PLEKHM3 gene has been associated with neuropathy and chordoma." (PMID 39062924, 2024).
glioma (1 paper, 2022). A benign or malignant brain and spinal cord tumor that arises from glial cells (astrocytes, oligodendrocytes, ependymal cells). "Potential diagnostic biomarkers MINK1, PLEKHM3, BZW1, and RCF2 had mRNA expression that differed significantly between GBM and the other glioma subtypes (p-values < 0.001)." (PMID 35877430, 2022).
ovarian tumor (1 paper, 2019). "CircPLEKHM3 was chosen for further investigation because its parental gene PLEKHM3 has not yet been studied in cancer and the PLEKHM3 was not significantly differentially expressed between ovarian tumor and normal tissues." (PMID 31623606, 2019).
tumor (5 papers, 2015 to 2022). "In this study, PLEKHM3 was significantly downregulated in GBM compared to non-tumor, and its expression and methylation were negatively and positively correlated, respectively, with IDH1 expression." (PMID 35877430, 2022). "Potentially, PLEKHM3 may have a similar tumor suppressor role in GBM that is influenced by IDH1 or α-ketoglutarate; however, this would need to be experimentally investigated." (PMID 35877430, 2022). "MINK1 and PLEKHM3 were significantly downregulated in GBM compared to non-tumor (p-values < 0.001)." (PMID 35877430, 2022). "Moreover, higher level of circ-PLEKHM3 was detected in xenograft tumor tissues in the transfection of oe-circ-PLEKHM3 group in the presence of DMSO or curcumin." (PMID 34784955, 2021). "Here, a comparison of gene expression between PLEKHM3 and IDH1 across the GBM tumor revealed the opposite trends, whereby PLEKHM3 was upregulated in the leading edge and downregulated in the cellular tumor." (PMID 35877430, 2022). "In addition, circ-PLEKHM3 overexpression enhanced curcumin-mediated promotion of c-caspase-3 and Bax protein expression, and reduction of PCNA protein expression in tumor tissues." (PMID 34784955, 2021).
cancer (3 papers, 2019 to 2023). A tumor composed of atypical neoplastic, often pleomorphic cells that invade other tissues. "In addition, the anti-cancer role of circ-PLEKHM3 was confirmed in our study, which was consistent with the previous study." (PMID 34784955, 2021). "Other ncRNAs involved in oxidative stress and inflammation-related disorders are circular RNAs such as circ-PRKCA, circ-ZNF83, circ-PLEKHM3, circ-FNDC3B, circ-102115 circSATB2 and circFOXM1 on which natural products modulation have been investigated on in cancers and other chronic diseases." (PMID 37168992, 2023). "Some circRNAs implicated in oxidative stress and inflammation-related disorders are circ-PRKCA, circ-ZNF83, circ-PLEKHM3, circ-FNDC3B, circ-102115 circSATB2 and circFOXM1 on which natural products modulation have been investigated in cancers and other disorders." (PMID 37168992, 2023).
PLEKHM3 also shares sentences with these, for which no sentence is quoted: infection (3 papers); breast carcinoma (1); hyperlipidaemia (1); Myocardial fibrosis (1); neurological diseases (1); neuropathy (1); septicemia (1).